RN7SL679P (RNA, 7SL, cytoplasmic 679, pseudogene)
Gene: Miscellaneous RNA gene on chromosome 1 (26,593,243 to 26,593,546, reverse strand). Ensembl gene ENSG00000243905.
Homologues: Orthologues: chimpanzee Metazoa_SRP (99% identical), macaque Metazoa_SRP (91% identical), pig Metazoa_SRP (79% identical). Paralogues in human: RN7SL1 (85% identical), RN7SL3 (85% identical), RN7SL2 (84% identical), RN7SL126P (82% identical), RN7SL664P (82% identical), RN7SL492P (82% identical), RN7SL296P (81% identical), RN7SL336P (81% identical), RN7SL559P (81% identical), Metazoa_SRP (81% identical), RN7SL14P (81% identical), RN7SL627P (81% identical), and 700 more.